MTDH (metadherin)
Diseases named in the same sentence as MTDH in open-access papers (continued):
Sharing a sentence is not in itself a finding about the gene and the disease.
breast carcinoma (continued). "Therefore, MTDH may promote breast cancer metastasis by regulating mRNA splicing through interacting with mRNAs or proteins of splicing factors." (PMID 31737791, 2019). "In addition, we found that MTDH, a metastasis adhesion gene that is frequently overexpressed in breast, prostate, liver, kidney and colon cancer, was a novel functional target of miR-320a in breast cancer." (PMID 27229534, 2016). "Taken together, these results demonstrated that miR-630 showed multifunction in breast cancer metastasis processes including suppresses the ability of migration, invasion as well as cancer cell reinitiated proliferation in distant organ which were mediated by MTDH." (PMID 26595523, 2016). "Thus, our study provides evidence that MTDH might be a potential novel biomarker effectively reflecting metastasis status and prognosis of breast cancer patients, which might help to formulate a better therapy for individual patient." (PMID 27917902, 2016). "Thus, it can be concluded that MTDH expressions in breast cancer cells are different due to different molecular phenotypes, and the overexpression of MTDH may be associated with the invasiveness and drug resistance of breast cancer cells." (PMID 25993398, 2015). "Furthermore, decreased tumor volume and Ki67 level as well as increased PTEN expression were observed after MTDH knockdown in subcutaneous breast cancer xenografts from SK-BR-3/R cells, while the opposite effect were found in grafts from MTDH overexpressing SK-BR-3 cells." (PMID 25417825, 2014). "MTDH over-expression has been detected in esophageal squamous cell carcinoma, gastric cancer, renal cancer, prostate cancer, non-small cell lung cancer, hepatocellular carcinoma, breast cancer, and neuroblastoma, compared to normal cells and the matched non-neoplastic regions." (PMID 23240043, 2012). "Metadherin (MTDH) is expressed on hepatocellular carcinoma, may play a role in epithelial-to-mesenchymal transition, and plays a role in the metastatic spread of breast cancer to the lung." (PMID 23251904, 2012). "However, there are no studies to date assessing variants of the MTDH gene and their potential relationship with breast cancer susceptibility." (PMID 21408129, 2011). "The discrepancy between the lack of correlation of the variants in the current study to disease progression in breast cancer (data not shown), and the previously documented high MTDH expression contributing to increased metastasis and poor prognosis warrants further discussion." (PMID 21408129, 2011). "Although previous studies found that MTDH could mediate lung metastasis of breast cancer, serve as a prognostic marker for progression and overall patient survival, whether MTDH involves in the progression of breast precancerous lesions to cancer is still unknown." (PMID 20565850, 2010). "Whether MTDH contributes to carcinogenesis of breast cancer is still unknown." (PMID 20565850, 2010). "In the present study, we revealed that S-palmitoylation of MTDH negatively regulates its interaction with ACSL4, thereby modulating the ferroptosis sensitivity in breast cancer cells." (PMID 41318030, 2025). "We observed the MTDH band shift in HAM treated group, affirming MTDH S-palmitoylation in HEK293T cells and several breast cancer cell lines." (PMID 41318030, 2025). "The subcellular locations of MTDH and QPCT in breast cancer cells were then examined by IF staining and laser confocal microscopy." (PMID 38417050, 2024). "In this novel research, bioinformatics has revealed the correlation between Metadherin and the tumor microenvironment (TME) in breast cancer for the very first time." (PMID 38253625, 2024). "In breast cancer, over-expression of OTUD6B‐AS1 has been found to promote autophagy and thus genomic instability via the lncRNA OTUD6B-AS1/miR-26a-5p/MTDH signalling pathway, this lncRNA promotes the progression of triple-negative breast cancer." (PMID 37781080, 2023).
breast carcinoma (continued). "The interaction between MTDH and SND1 is critical for its oncogenic function in breast cancer and disruption of this interaction results in suppression of cancer progression and metastasis." (PMID 37973913, 2023). "Inhibition of SIRT1 with either EX-527 or SIRT1 siRNA resulted in the upregulation of c-Myc (a pro-oncogenic protein) and MTDH (an oncogenic protein) in MDA-MB-231 and BT-549 breast cancer cells." (PMID 36291902, 2022). "On the other hand, it has been reported that the overexpression of MTDH promotes PTX resistance, tamoxifen resistance and doxorubicin resistance in luminal-A and TNBC breast cancer." (PMID 34740994, 2021). "Numerous studies have reported that MTDH can promote CSC characteristics in colorectal cancer, glioblastoma cancer, pancreatic cancer, and breast cancer." (PMID 31979093, 2020). "Ectopic expression of miR-128 in human breast cancer cell line MDA-MB-231 impaired cell migration and invasion capability by targeting Metadherin (MTDH)." (PMID 32993809, 2020). "Metadherin (MTDH), which was overexpressed and predicted a poor prognosis in cancer, conferred a therapy-resistant mesenchymal-high state in breast cancer cells, but also increased sensitivity to ferroptosis by downregulating GPX4 and SLC3A2." (PMID 33292585, 2020). "Xena browser analysis revealed a positive correlation between MTDH and the BCSC marker CD44 in breast cancer patients." (PMID 31979093, 2020). "Metadherin (MTDH), a protein that is overexpressed in metastatic breast cancer, can bind to the vasculature of the lung, a common site of breast cancer metastasis." (PMID 32943996, 2020). "Xena browser analysis also revealed a positive correlation between the MTDH and CD44 expression levels in The Cancer Genome Atlas (TCGA) breast cancer database (n = 1247, r = 0.05725, p-value = 0.04586)." (PMID 31979093, 2020). "Furthermore, MTDH, an oncogene regulating biological functions such as cell metabolism, survival, apoptosis, angiogenesis, etc., was identified as a direct target gene of miR-128 and involved in miR-128-mediated suppression of migration and invasion in breast cancer cells." (PMID 32993809, 2020). "MTDH correlates positively with the gene sets enriched in either EMT or metastasis in various types of cancer, including basal-like breast cancer, lung adenocarcinoma, lung squamous carcinoma, and endometrial cancers." (PMID 31527591, 2019). "Thus, MTDH may represent an interesting therapeutic target for treatment of HER2+ breast cancers." (PMID 31131259, 2019). "Based on these findings, we explored the relationship between MTDH gene expression and TAX resistance in breast cancer cell lines as well as the effect of MTDH knockdown on TAX therapeutic efficiency." (PMID 30227879, 2018). "Taken together, our results suggest that MTDH expression plays a crucial role in the MCF-7 breast cancer cell proliferation and is potentially useful for breast cancer treatment." (PMID 30227879, 2018). "In breast cancer cells, MTDH overexpression promoted cancer cells to undergo EMT, while MTDH knockdown reversed EMT changes." (PMID 28107197, 2017). "Previous experimental data indicated that MTDH regulates EMT and promotes CSC accumulation in breast cancer." (PMID 29029495, 2017). "In addition, MTDH could regulate TWIST expression in breast cancer cells." (PMID 28107197, 2017). "The effect of metformin treatment on breast cancer cell viability and miR-26a, BCL-2, PTEN, MCL-1, EZH2, and MTDH modulation were evaluated." (PMID 27517917, 2016). "Increased MTDH promotes HRAS induced tumor-promoting effects, facilitates breast cancer metastasis, and activates NFκB transcription through accumulating nuclear translocation of p65 in Hela cells." (PMID 26683226, 2016). "To conclude, these results indicate that MTDH and VDAC1 are potential targets of miR-320a in breast cancer." (PMID 27229534, 2016).
breast carcinoma (continued). "miR-26a/b have also been reported to induce cell apoptosis by targeting MTDH, EZH2 and SLC7A11 in breast cancer cells and by targeting SODD in melanoma cells." (PMID 24565101, 2014). "MTDH mediates trastuzumab resistance, at least in part, through PTEN-PI3K/Akt signaling in an NFκB dependent pathway in HER2 positive breast cancer." (PMID 25417825, 2014). "In breast cancer cells, AEG-1/MTDH facilitates cancer proliferation and invasion by upregulating HER2/neu expression." (PMID 25009642, 2014). "AEG-1/MTDH also downregulates the transcriptional activity of forkhead box (FOXO) 1 through the PI3K/Akt signaling pathway in MCF-7 and MDA-MB-435 breast cancer cells." (PMID 25009642, 2014). "Up-regulation of miR-26a promotes apoptosis in rat neonatal cardiomyocytes via the caspase-3 pathway while down-regulation of miR-26a antagonizes apoptosis by targeting MTDH and EZH2 in breast cancer." (PMID 25070658, 2014). "Blocking AEG-1/MTDH and its regulated pathways is likely to be beneficial in breast cancer cells or tissues." (PMID 25009642, 2014). "The correlations between MTDH and PTEN expressions were analyzed both in HER2 positive breast cancer tissues and trastuzumab resistant SK-BR-3 (SK-BR-3/R) cells." (PMID 25417825, 2014). "In unsupervised hierarchical clustering a distinctive group of male breast cancer with poor prognosis (p = 0.009; hazard ratio 3.4) was identified, characterized by frequent CCND1, MTDH, CDC6, ADAM9, TRAF4 and MYC copy number gain." (PMID 22527098, 2012). "The study also revealed that miR-375 directly targets metadherin (MTDH) and that there is an inverse correlation between the expression of miR-375 and MTDH in primary breast cancer cell lines." (PMID 23202960, 2012). "The results suggested that LPS upregulated the MTDH expression in time-dependent and concentration-dependent manners in TLR4 positive breast cancer cells." (PMID 22195048, 2011). "MTDH, (also known as astrocyte elevated gene-1, AEG-1 and Lyric), is a newly cloned gene, which has aberrantly higher copy numbers at 8q22 in breast cancer patients." (PMID 22195048, 2011). "A “lung homing domain”, which mediates lung metastasis in the 4T1 mouse mammary tumor cell, was identified in MTDH in 2004 with phage display screening and was subsequently named metadherin." (PMID 21408129, 2011). "We also examined the correlation between MTDH expression and common proliferative marker Ki67 in DCIS and breast cancer." (PMID 20565850, 2010). "By targeting MTDH degradation, FBXW7 can also suppress breast cancer growth and induce apoptosis." (PMID 39823500, 2025). "Since we showed that VCP activity controls basal MTDH expression levels, the careful use of pharmacological VCP activators might attenuate the progression of breast cancer." (PMID 38727283, 2024). "Collectively, our findings delineate the mechanism by which the MTDH/NF-κB (p65) axis regulate QPCT signaling and suggest that this complex may play an essential role in breast cancer progression and affect DOX sensitivity." (PMID 38417050, 2024). "MTDH depletion or pharmacological inhibition disrupts the interaction with staphylococcal nuclease domain-containing 1 (SND1), which is required to sustain breast cancer progression in established tumors." (PMID 38727283, 2024). "Total knockout of Metadherin expression in mice does not affect embryogenesis or postnatal development; however, it severely affects mammary tumor formation." (PMID 38253625, 2024). "Among the predictions with the lowest scores, MTDH has been shown to epigenetically regulate TWIST1 and promote stemness in breast cancer while AKAP12 has been suggested to protect ERK5 from PKCζ phosphorylation on residue S486A which inhibits its transcriptional activity." (PMID 37420093, 2023).
breast carcinoma (continued). "SIRT1 has been demonstrated to modulate several intracellular signaling protein molecules, including protein kinase B (PKB), B-cell lymphoma 2 (Bcl-2), metadherin (MTDH), Frizzled 7, EMT-related proteins, and the cluster of differentiation 36 (CD36), in breast cancer cells." (PMID 36291902, 2022). "MiR-26a directly targets several anti-apoptotic proteins, such as E2F Transcription Factor 3 (E2F3), myeloid cell leukaemia-1 (Mcl-1), metadherin (MTDH), enhancer of zeste homolog 2 (EZH2), and phosphatase and tensin homolog (PTEN) which are up-regulated in breast cancer." (PMID 33849540, 2021). "Additionally, we found an inverse correlation of MTDH and RKIP expression in patient breast cancer cohort from TCGA." (PMID 33802672, 2021). "As MTDH has been reported to play a prominent role in breast cancer therapy resistance and maintenance of the CSC population, we examined whether MTDH could play a role in the stemness of MDA-MB-231/IR cells." (PMID 31979093, 2020). "Moreover, there was a positive correlation between the MTDH and CD44 expression levels in The Cancer Genome Atlas breast cancer database." (PMID 31979093, 2020). "MTDH and IL-10 protein expression of breast cancer patients usually harbored negative estrogen receptor (ER) or progesterone receptor (PR) status, and late-stage tumors have higher IL-10 expression." (PMID 33003428, 2020). "Increased expression of mRNAs alternative splicing isoforms derived from alteration of splicing factors and MTDH expression could promote EMT and breast cancer metastasis, which provides new targets for breast cancer therapy." (PMID 31737791, 2019). "In a cohort of 44 neoadjuvant chemotherapy breast cancer patients, 29 patients were MTDH gene positive and 15 patients were negative." (PMID 30227879, 2018). "Based on these findings, we subsequently synthesized a polymeric NP that could co-deliver MTDH-small interfering RNA (MTDH–siRNA) and TAX into the breast cancer tumors in tumor-bearing mice." (PMID 30227879, 2018). "Metadherin (MTDH), as a cell surface protein, could induce breast cancer cells transferring to lung in mouse model." (PMID 27917902, 2016). "We checked the gene expression levels of MCL-1, MTDH, and EZH2 which are proven targets of miR-26a in breast cancer and could be responsible of its anti-proliferative effect." (PMID 27517917, 2016). "Moreover, our study has identified MTDH, a multifaceted oncogene which activate AKT, NFκB, and Wnt/β-catenin signal pathways, as the direct target of miR-630 in breast cancer cells." (PMID 26595523, 2016). "Elevated MTDH expression indicated poor clinical benefit, shortened progression free survival time, and was negatively correlated with PTEN level both in HER2 positive breast cancer patients and SK-BR-3/R cells." (PMID 25417825, 2014). "Transfection of a recombinant plasmid containing pcDNA-AEG-1/MTDH-microRNA (miR)-4 significantly suppresses AEG-1/MTDH at the mRNA and protein levels by >69% in MDA-MB-231 breast cancer cells, and significantly inhibits proliferation, motility and migration compared with controls." (PMID 25009642, 2014). "In HCC and breast cancer, genomic amplification of AEG-1/MTDH has been found in patients." (PMID 25009642, 2014). "Recently, Li reported that MTDH was not expressed in normal mammary epithelial cells, but expressed with different extent in breast cancer cell lines." (PMID 23984913, 2013). "Subsequently, the human MTDH gene was localized at chromosome 8q22 and has been reported to be amplified in a number of malignancies such as malignant glioma, hepatocellular carcinoma (HCC), and breast cancer." (PMID 21408129, 2011). "In summary, induction of MTDH by LPS could increase the migration and invasiveness in the TLR4 positive breast cancer cells." (PMID 22195048, 2011). "Other known breast cancer gene target such as ERBB2, E2F1 and MTDH are in the global driver list." (PMID 21806811, 2011).
breast carcinoma (continued). "Taken together, these findings suggest that S-palmitoylation of MTDH enhances ferroptosis sensitivity in breast cancer cells, may particularly in MDA-MB-231, but not in estrogen receptor-positive (ER+) MCF7 cells." (PMID 41318030, 2025). "Metadherin was not significantly correlated with PPS in breast cancer." (PMID 38253625, 2024). "In addition, a large number of studies have reported that Huaier extract, the Huaier polysaccharide, can enhance the immunity, antioxidation, and anti-inflammatory responses and downregulate Metadherin (MTDH) expression, which finally induces apoptosis in MCF-7 breast cancer cells." (PMID 32724797, 2020). "Several studies on breast cancer have shown that miR-26a can inhibit cell proliferation, colony formation and migration, as well as promote apoptosis by regulating several carcinogenesis-related processes, including several mechanisms that involve the targeting of MCL-1, MTDH and EZH2." (PMID 25184951, 2014). "MTDH mediates trastuzumab resistance, at least in part, by PTEN inhibition through an NFκB-dependent pathway, which may be utilized as a promising therapeutic target for HER2 positive breast cancer." (PMID 25417825, 2014). "In the present study, we investigated the expression of MTDH in normal, UDH (usual ductal hyperplasia), ADH (atypical ductal hyperplasia), DCIS (ductal carcinoma in situ) and invasive cancer to explore the possible role of MTDH for breast cancer carcinogenesis." (PMID 20565850, 2010). "Moreover, without MTDH, treatment with EX-527 will significantly increase breast cancer cell death." (PMID 38728242, 2024). "Further, in the presence of c-Myc siRNA, EX-527 could not upregulate MTDH in breast cancer cells." (PMID 36291902, 2022). "The non-S-palmitoylation form of MTDH-CS enhanced the interaction between MTDH and the ferroptosis enhancer of Acyl-CoA synthetase long-chain family member 4 (ACSL4), thereby reducing ferroptosis sensitivity in breast cancer cells." (PMID 41318030, 2025). "AEG-1/MTDH is expressed at low levels or is absent in the majority of normal human breast tissues, but is frequently overexpressed in ductal carcinoma in situ, breast cancer cell lines or breast tumors." (PMID 25009642, 2014).